INS (insulin)
Diseases named in the same sentence as INS in open-access papers (continued):
Sharing a sentence is not in itself a finding about the gene and the disease.
Insulin resistance (continued). "We calculated multiple indices for insulin resistance and insulin secretory function but were limited to indices that use these timepoints." (PMID 39621104, 2025). "In individuals with prediabetes, insulin resistance results from defects in the insulin signalling pathways." (PMID 41296388, 2025). "In the early stages, the pancreas compensates for insulin resistance by increasing insulin production." (PMID 40944248, 2025). "Insulin resistance becomes pathological when the adaptive reduction in insulin sensitivity persists or is exaggerated in response to modern environmental stressors." (PMID 40565766, 2025). "Measures of insulin resistance, including fasting insulin and homeostasis model assessment of HOMA-IR, were significantly higher in the T2DM obese group than in both the euglycemic obese and control groups (p < 0.001)." (PMID 41422312, 2025). "In light of this, the aim of this study was to evaluate the relationship between AGE intake and insulin resistance and if the ability of these glycotoxins to predict deterioration of insulin sensitivity is sex-dependent." (PMID 40263184, 2025). "HFD-induced elevation of serum insulin was greater in SIRPαloxp/loxp mice than in SIRPαΔMac mice, suggesting exacerbated insulin resistance in SIRPαloxp/loxp mice." (PMID 40016734, 2025). "While T2D patients still produce insulin, many require insulin therapy to achieve desired glycemic control, due in part to the development of insulin resistance." (PMID 41531706, 2025). "Fasting blood glucose was measured using a glucometer, and the homeostasis model assessment of insulin resistance (HOMA-IR) was calculated using fasting serum insulin levels." (PMID 40600138, 2025). "PPARγ inhibitor and PPARγ knockdown abolished the improvement of insulin resistance by Metrnl, suggesting that the increase in insulin sensitivity by Metrnl is mediated by PPARγ signaling." (PMID 40956671, 2025). "HFD is known to trigger β-cell mass expansion through enhanced β-cell proliferation, a response that can either precede or follow the onset of insulin resistance, resulting in a compensatory increase in insulin secretion to correct hyperglycemia." (PMID 40066865, 2025). "It was observed that insulin-resistant mice showed significant improvement in insulin resistance following treatment with RSV." (PMID 40661966, 2025). "Thiamine and pyridoxine play crucial roles in glucose metabolism and insulin function, impacting insulin resistance." (PMID 39791169, 2025). "Meanwhile, the C-1 (15 or 30 mg/kg) decreased the glucose, insulin, and insulin resistance index by 53, 47, and 75 % for group 3 and 78, 51, and 83 % for the group 4 compared to group 2." (PMID 39962072, 2025). "Obesity, as a chronic inflammatory condition, disrupts tissue insulin sensitivity and function, leading to the development of T2D and adipocyte insulin resistance (IR)." (PMID 40629272, 2025). "Chronic inflammation, intramyocellular lipid buildup, and mitochondrial dysfunction all impair insulin signaling and worsen muscle insulin resistance." (PMID 40870444, 2025). "Obesity indicators included body weight and epididymal fat, while insulin resistance was measured by fasting serum glucose, serum insulin, homeostasis model assessment–insulin resistance index (HOMA-IR), and oral glucose tolerance (OGTT)." (PMID 40427477, 2025). "It is established that oxidative stress can impair the insulin signaling pathway and is considered one of the key drivers of insulin resistance in T2DM patients." (PMID 40369521, 2025). "This release of NF-κB initiates transcription of pro-inflammatory genes, impairing insulin signaling and contributing to insulin resistance." (PMID 39762333, 2025). "This has led to the concept of pathway-specific hepatic insulin resistance, where the insulin activation pathway involving protein kinase B/forkhead box protein O1 is inhibited, while the SREBP-1c pathway remains activated." (PMID 40893881, 2025).
Insulin resistance (continued). "GTT results revealed higher glycemic levels at baseline, 15, and 30 min following glucose administration, while the ITT showed elevated glucose levels at 3 min post-insulin injection, indicating early signs of insulin resistance." (PMID 40805981, 2025). "Rapamycin therapy, for instance, can lead to more severe insulin resistance, likely because it also impairs the stability of the mTORC2 complex, thereby dampening the Akt-dependent insulin response." (PMID 41356921, 2025). "Despite the complex and bidirectional relationship between insulin sensitivity and insulin secretion, elevated insulin levels are often presented as a compensatory β-cell response to insulin resistance." (PMID 40013621, 2025). "Once insulin resistance is settled, a default of insulin action impairs glucose uptake and glucose disposal leading to chronic hyperglycemia." (PMID 40943107, 2025). "Their analysis concluded that PCOS patients exhibited significantly greater insulin resistance relative to ovulatory controls, even after adjusting for BMI, fasting glucose, and insulin concentrations." (PMID 40226143, 2025). "A further connection between insulin resistance and TGF-β signaling in the liver is implicated by the effects of insulin and TGF-β on the function of diseased liver." (PMID 40260391, 2025). "Insulin resistance occurs when cells in the body become less responsive to insulin, resulting in higher blood glucose levels and eventual dysfunction of pancreatic beta cells, which produce insulin." (PMID 40137394, 2025). "The homeostasis model assessment of insulin resistance results and composite insulin sensitivity index of the high FLI group were higher than those of the other groups (P < 0.0001)." (PMID 40570015, 2025). "And feeding these bacteria leads to impaired insulin sensitivity and glucose tolerance, highlighting the role of BCAAs and their metabolizing bacteria in the development of insulin resistance." (PMID 40260760, 2025). "Future studies should comprehensively assess the effect of auricular acupressure on insulin metabolism by measuring insulin resistance indices (e.g., HOMA-IR) and insulin secretion function (e.g., C-peptide)." (PMID 41293201, 2025). "In contrast, T2DM, representing 90–95% of cases, involves insulin resistance and inadequate compensatory insulin secretion." (PMID 41463606, 2025). "Both T2DM and AD share common characteristics, including inflammation, alteration of insulin signaling, insulin resistance, and glucose metabolism." (PMID 40943177, 2025). "An oral glucose tolerance test (OGTT) was used to calculate insulin resistance and insulin sensitivity as measures of metabolic function, while dual-energy x-ray absorptiometry and computed tomography were used to assess body composition." (PMID 41228532, 2025). "Pioglitazone, a potent insulin sensitizer, enhances insulin action in muscle by activating PPARγ receptors and is widely used in T2D treatment to reduce insulin resistance." (PMID 39998445, 2025). "In essence, the requirement for insulin increased with the degree of insulin resistance following the sequence of cluster‐β < cluster‐mixed < cluster‐IR." (PMID 39810724, 2025). "Insulin resistance, defined as the failure of insulin-dependent cells responding normally for insulin, plays a crucial role in the initiation and progression of DM and atherosclerosis." (PMID 41573503, 2025). "PCE offspring presented decreased basal serum glucose, insulin, and insulin resistance index, accompanied by improved glucose tolerance and insulin sensitivity." (PMID 40903796, 2025). "The accumulation of PA was reported to lead to insulin resistance by affecting genes in the insulin signaling pathway." (PMID 40878918, 2025). "Clinically, circulating PLTP activity was shown to be positively associated with metabolic parameters such as waist circumference, fasting glucose, fasting insulin, insulin resistance, and hemoglobin A1c." (PMID 40658727, 2025).
Insulin resistance (continued). "Although not measured in the current study, previous work has reported that ZDSD animals have elevated blood insulin by 13 weeks and exhibit substantial insulin resistance." (PMID 40337247, 2025). "In obesity, serine serves as a precursor for sphingolipid synthesis, promoting the accumulation of bioactive lipid ceramides in insulin-sensitive tissues such as the liver and muscle, thereby exacerbating insulin resistance." (PMID 40438394, 2025). "Insulin resistance (IR) is a metabolic condition characterized by the reduced ability of insulin to perform its role in glucose uptake and utilization." (PMID 40422918, 2025). "These adipokines are intrinsically associated with insulin sensitivity: high levels of resistin and PAI-I are associated with insulin resistance, while high levels of adiponectin are associated with insulin sensitivity." (PMID 41322229, 2025). "One key molecular defect that appears to underpin insulin resistance in skeletal muscle is defective trafficking of the glucose transporter GLUT4 to the cell membrane in response to insulin signalling in a temporally appropriate manner." (PMID 40495716, 2025). "In states of hyperinsulinemia, a precursor to insulin resistance, Nrf2 expression is suppressed via insulin’s induction of heterogeneous ribonucleoproteins F and K, leading to an impaired antioxidant and cyto-protective defense capacity." (PMID 40573148, 2025). "Previous studies indicated higher level of ADMA causes insulin resistance and T2D, whereas higher expression of DDAH2 improves glucose-stimulated insulin secretion." (PMID 40864748, 2025). "The disruption of insulin function, characterized by insulin resistance, results in impaired ATP7B activity and subsequent intracellular Cu accumulation." (PMID 41301408, 2025). "Elevated plasma BCAA levels have been consistently observed in diabetic patients and animal models, with clinical studies linking them to insulin resistance (positive association with HOMA-IR) and impaired F-INS secretion." (PMID 40636076, 2025). "One patient had a history of macrosomia and hypercholesterolemia, while the other presented with insulin resistance requiring insulin and metformin therapy." (PMID 41367630, 2025). "NAC, an antioxidant and insulin sensitizer, has been found to improve insulin resistance and ovulation rates." (PMID 40357783, 2025). "Previous research has shown that GDM-IFH is closely related to hepatic insulin sensitivity and subsequent hepatic glucose production, whereas GDM-IPH is closely associated with muscle insulin resistance." (PMID 41036090, 2025). "The experimental validation shows that the application of insulin is beneficial to relieve inflammation and oxidative stress, hence probably decrease the insulin resistance." (PMID 40641746, 2025). "As β-cell function declines during T2DM progression, insulin resistance in peripheral tissues is paired with insufficient insulin production." (PMID 41226411, 2025). "In cases of insulin resistance or insufficient insulin, LDL clearance is slowed, triglyceride (TG) hydrolysis is inhibited, and blood levels of TG and LDL increase." (PMID 40336535, 2025). "Prior to menopause, women typically exhibit elevated estrogen levels, which can enhance insulin sensitivity by activating the AMPK signaling pathway and reducing visceral fat accumulation, thereby decreasing the risk of insulin resistance." (PMID 40626240, 2025). "In our study, patients with insulin resistance demonstrated elevated insulin levels characterized by compensatory hyperinsulinemia." (PMID 41300682, 2025). "IR is a critical biomarker for MetS, with several key indicators including insulin, C-peptide, and the Homeostatic Model Assessment of Insulin Resistance (HOMA-IR)." (PMID 40051521, 2025).
Insulin resistance (continued). "Furthermore, MGO may exert its effects via modification of important hormonal and enzymatic targets, such as insulin and its signaling components (causing insulin resistance), AMPK (amplifying anabolic processes), as well as collagen (leading to fibrosis/cirrhosis through ECM dysfunction)." (PMID 40141037, 2025). "Primary among these is the age-related decline in insulin sensitivity, an essential component in the emergence of insulin resistance, a quintessential feature of T2DM, which is known to intensify with advancing years." (PMID 40444231, 2025). "HOMA-IR, a tool for the assessment of insulin resistance based on fasting insulin and glucose levels, was significantly decreased by about 4.3 folds compared to CON rats, which was significantly recovered by AHRE." (PMID 41189666, 2025). "FGF-19 has been increasingly studied for its role in metabolic regulation, particularly in the context of insulin resistance (IR), and appears to influence insulin sensitivity." (PMID 41169463, 2025). "Metabolic correlations with total lipids, triglycerides, low-density lipids, and fasting glucose and insulin suggested IL-6's role in insulin resistance." (PMID 40226143, 2025). "We deployed both insulin and C-peptide based estimates of insulin resistance, β-cell function, and oDI in our study." (PMID 40544417, 2025). "Insulin resistance is a pathological condition of the body that is defined by reduced insulin biological effects, even at high concentrations, which causes problems with glucose uptake and transportation." (PMID 41370421, 2025). "This insulin-independent mechanism is particularly beneficial for individuals with insulin resistance, as it provides an alternative pathway for lowering blood sugar levels and reducing the pancreas’s workload." (PMID 40362807, 2025). "Inflammatory mediators influence insulin signaling pathways, therefore affecting the secretion of insulin and modulating insulin resistance." (PMID 41585812, 2025). "Insulin resistance elevates insulin levels and promotes adipocyte lipid accumulation, resulting in obesity, thereby heightening the susceptibility to T2DM." (PMID 40671123, 2025). "Skeletal muscle, being the primary target for insulin-mediated glucose uptake, plays a crucial role in the pathogenesis of insulin resistance in the elderly." (PMID 41357171, 2025). "Compared to the Con group, mice in the Mod group exhibited significantly elevated INS and IR (p < 0.001), along with significantly reduced ISI, indicating the onset of insulin resistance and diminished insulin sensitivity in the model mice." (PMID 40170727, 2025). "Insulin resistance as measured by comparing the ratio of fasting glucose level to fasting insulin level (HOMA-IR) was also unchanged between controls and C3aR1-MφKO mice." (PMID 39773465, 2025). "Under insulin resistance conditions, insulin signaling shifts toward pro‐inflammatory pathways, disrupting normal metabolic processes." (PMID 40951581, 2025). "It is well known that cerebrovascular abnormalities, particularly ischemic stroke, can exacerbate insulin resistance by enhancing inflammation and oxidative stress which, in turn, disrupt insulin signaling and glucose homeostasis." (PMID 41114083, 2025). "Given that skeletal muscle is the main tissue responsible for tissue glucose utilization and insulin action, and is, therefore, considered a major site for the development of insulin resistance and type 2 diabetes, this finding is important." (PMID 39857794, 2025). "For instance, most people with MetS also suffer from insulin resistance making it more difficult for tissues/organs in the body to respond to insulin and to uptake glucose, but these effects cannot be captured within the WBMs." (PMID 40470351, 2025). "HOMA-IR is a method for estimating insulin resistance (calculated using fasting glucose and fasting insulin levels), with a higher value indicating greater insulin resistance." (PMID 40564223, 2025).
Insulin resistance (continued). "High plasma uric acid directly inhibits insulin signaling inducing insulin resistance, and we showed that NT5C2 deletion in mice lowered HFD-induced hyperuricemia." (PMID 39947478, 2025). "Insulin resistance, hyperinsulinemia, and excess activation of the insulin signaling pathway have been identified as key drivers of aging-related chronic inflammation, which is often called inflammaging." (PMID 41228532, 2025). "As insulin resistance develops, the liver becomes less sensitive to insulin, which decreases glucose uptake and increases glucose production by the liver, which in turn worsens hyperglycemia." (PMID 41220583, 2025). "An HFD induces hyperglycemia and insulin resistance, which prompts compensatory proliferation of islet β-cells to meet insulin demands." (PMID 40842956, 2025). "These pro-inflammatory cytokines, particularly TNF-α and IL-6, can lead to insulin resistance in adipose tissue, skeletal muscle, and the liver by disrupting insulin signaling." (PMID 40689212, 2025). "Patients with baseline insulin resistance (i.e., fasting insulin >20 μU/mL; n = 11) exhibited significant decreased fasting insulin after treatment." (PMID 40444533, 2025). "It is well established that dietary fructose promotes insulin resistance via several metabolic pathways that interplay and lead to increased blood glucose and insulin levels, and decreased insulin sensitivity." (PMID 41465047, 2025). "On top of this, correction of vitamin D levels is a comparatively low‐risk intervention that has also been related to lowering HbA1c levels, reducing insulin resistance and improving insulin sensitivity." (PMID 41139799, 2025). "While T1D involves autoantibodies against insulin-producing cells, T2D’s immune role centers on low-grade inflammation and insulin resistance." (PMID 40597162, 2025). "In vivo administration of EVs from HFD-fed mice induced insulin resistance and glucose intolerance compared to RD-fed mice; Pseudomonas panacis-derived EVs blocked the insulin signaling pathway in both skeletal muscle and adipose tissue." (PMID 40129979, 2025). "Insulin resistance (IR) is defined as the lack or decreased response of the target tissues to insulin." (PMID 40416375, 2025). "↓ Blood glucose, ↓ insulin levels, ↓ insulin resistance, ↓ homeostatic model assessment of insulin resistance (HOMA-IR), preserved pancreatic β-cells integrity, ↓ serum MDA levels, and ↑ serum SOD levels." (PMID 40722870, 2025). "Another study confirmed these findings, demonstrating that arsenic exposure in HFD-fed mice reduced fasting insulin, insulin resistance, β-cell dysfunction, and systemic insulin resistance." (PMID 40726918, 2025). "In a state of insulin resistance, β-cell depletion to maintain normoglycemia and compensate for insulin demand is critical to the pathogenesis of the condition." (PMID 40881124, 2025). "One school argues that insulin resistance stems from defects in the proximal insulin signalling cascade." (PMID 40806697, 2025). "Even in the presence of severe insulin resistance, fully functional β-cells can produce sufficient insulin to counterbalance impaired insulin action." (PMID 40004800, 2025). "This heightened oxidative stress can impair the function of pancreatic β-cells; this situation contributes to insulin resistance, making it harder for cells to use insulin to absorb glucose from the blood." (PMID 41007307, 2025). "These compounds have been scientifically proven to have anti-diabetic effects by either increasing insulin secretion from the pancreas or reducing insulin resistance." (PMID 40438603, 2025). "Insulin resistance results in impaired peripheral glucose and a failure of insulin to suppress hepatic gluconeogenesis and lipolysis." (PMID 40583967, 2025). "TNF-α overexpression in adipose tissue decreases peripheral glucose uptake in response to insulin, leading to insulin resistance." (PMID 40362446, 2025).